PLOD2 (procollagen-lysine,2-oxoglutarate 5-dioxygenase 2)
Diseases named in the same sentence as PLOD2 in open-access papers (continued):
Sharing a sentence is not in itself a finding about the gene and the disease.
serous ovarian tumors (1 paper, 2008). "For example, TMEM158, HEG1, PLOD2 and ATP13A3, were recently found differentially expressed greater than 3-fold in a comparative analysis of primary cultures of normal ovarian surface epithelial cells and malignant serous ovarian tumors." (PMID 18687136, 2008).
signet ring cell carcinoma (1 paper, 2022). A usually aggressive, poorly differentiated invasive adenocarcinoma characterized by the presence of malignant glandular cells in which the nucleus is pressed to one side by the presence of intracytoplasmic mucus. "In addition, immunohistochemical results showed that in the high PLOD2 group, the clinical stages were mainly stage III and stage IV, and the proportion of signet ring cell carcinoma was also higher." (PMID 35586565, 2022).
soft tissue sarcoma (1 paper, 2021). A malignant neoplasm arising from muscle tissue, adipose tissue, blood vessels, fibrous tissue, or other supportive tissues excluding the bones. "Previous studies have shown correlation of PLOD2 expression with metastatic potential in soft tissue sarcoma akin to our discoveries in RMS." (PMID 33708626, 2021).
spinal cord injury (1 paper, 2023). Penetrating and non-penetrating injuries to the spinal cord resulting from traumatic external forces (e.g., WOUNDS, GUNSHOT; WHIPLASH INJURIES; etc.). "In the context of spinal cord injury (SCI), ADMSC transplantation has been shown to upregulate the expression of procollagen-lysine, 2-oxoglutarate 5-dioxygenase 2 (PLOD2), which is a lysyl hydroxylase enzyme." (PMID 38004615, 2023).
Stillbirth (1 paper, 2023). Death of the fetus in utero after at least 22 weeks of gestation. "Though the study was limited in ascertaining de novo from inherited variants, due to unavailability of paternal DNA, genes were reported by the authors that are either lethal, known to cause disease, or increase stillbirth risk (e.g., CCR5, FAT1, FLNB, INPP5K, MYO1C, PLOD2)." (PMID 36800380, 2023).
synovitis (1 paper, 2022). Inflammation of a synovial membrane. "Effects of synovitis ointment on bone cell fibrosis were detected through Masson staining, and the relative mRNA expression of PLOD2, COL1A1, TIMP1, and TGF-β was observed using the real-time quantitative (RT-PCR) method." (PMID 35815270, 2022). "To verify the effects of synovitis ointment on bone cells fibrosis, through RT-PCR assays, we examined the relative mRNA expression of PLOD2, COL1A1, TIMP1, and TGF-β under different treatment conditions." (PMID 35815270, 2022). "As expected, synovitis ointment decreased the levels of PLOD2, COL1A1, TIMP1, and TGF-β." (PMID 35815270, 2022). "While, the relative mRNA expression of PLOD2, COL1A1, TIMP1, and TGF-β was significantly decreased in the synovitis ointment group." (PMID 35815270, 2022). "The levels of PLOD2, COL1A1, TIMP1, and TGF-β were significantly higher in those lacking drug treatments than those treated with synovitis ointment (P < 0.05)." (PMID 35815270, 2022).
undifferentiated pleomorphic sarcoma (1 paper, 2020). An undifferentiated soft tissue sarcoma characterized by the presence of a pleomorphic malignant cellular infiltrate. "Similar involvement of LOX in tumour dissemination was reported for undifferentiated pleomorphic sarcoma (UPS), where HIF1 alpha promoted the expression of PLOD2, and PLOD2 inhibition led to a decrease in collagen deposition, organisation and maturation, and a decrease in lung metastases." (PMID 33066583, 2020).
tumor (107 papers, 2005 to 2026). "High PLOD2 expression in clinical samples was associated with ccRCC progression and potentially enhanced sensitivity to immunotherapy by modulating tumor mutational burden and immune escape-related pathways." (PMID 41584042, 2026). "Recent studies have implicated the PLOD family, particularly PLOD2, in tumour progression, invasion, and metastasis." (PMID 40673276, 2025). "Our exploration of intercellular communications involving PLOD2 + SAA1 + tumor cells provides insights into the underlying molecular mechanisms driving tumor development and metastasis." (PMID 38951896, 2024). "It has been reported that PLOD2 exhibits significant upregulation in various cancers, and its elevation is closely associated with tumor progression." (PMID 38008826, 2023). "All in all, the results of our study provide information regarding the role of PLOD2 in tumors, reveal the relationship between PLOD2 and tumor-immune interactions, and clarify the potential underlying mechanisms." (PMID 35586565, 2022). "In these cancer tissues, PLOD2 is significantly overexpressed, and the high PLOD2 expression was significantly associated with tumor metastasis and shorter survival time." (PMID 35141213, 2021). "Silencing PLOD2 expression in cancer-associated fibroblasts significantly reduces tumor invasion and metastasis." (PMID 33692828, 2021). "Cox proportional regression model was used to identify a four-gene (WIPF1, PPIB, BASP1, PLOD2) signature that were significantly associated with overall survival (OS), and all the four genes were significantly upregulated in tumor tissues." (PMID 34257533, 2021). "Expression of COL18A1 and PLOD2 is associated with increased tumor infiltration, metastasis, and worse overall survival and thus offer potential therapeutic targets." (PMID 33708626, 2021). "The remarkable association between PLOD1 (P = 0.009) and PLOD2 (P < 0.0001) expressions and tumor grade was observed." (PMID 33014843, 2020). "In HIF-1α-deficient tumors, ectopic PLOD2 expression restores the migration and metastatic potential, and inhibition of PLOD2 activity suppresses the tumor metastases." (PMID 30003082, 2018). "Compared with normal kidney, the ECM components and mechanics-associated genes (from PLOD2 to ICAM1) in tumor tissues were significantly increased in ccRCC patients." (PMID 28846080, 2017). "Immunohistochemistry demonstrated that increasing PLOD2 protein levels were associated with increasing tumor grade." (PMID 28423580, 2017). "Specifically, PLOD2 depletion in cancer-associated fibroblasts (CAFs) reportedly abrogate the ability of them to promote tumour cell invasion and migration in vitro and in vivo." (PMID 28507454, 2017). "The downregulated genes (DEPTOR, DPEP1, NAT8, and SUSD2) in the tumor and thrombus were associated with a worse survival rate when the gene was less expressed in the tumor, and the same correlation was observed for the upregulated genes (PLOD2 and SLC7A5)." (PMID 37328520, 2023). "Here, we investigated whether the protein levels of PLOD2 in tumor tissue are associated with overall survival (OS) or progression-free survival (PFS) of GBM patients with confirmed IDH wild-type (IDH WT) status." (PMID 35682709, 2022). "In terms of mechanism, PLOD2 induced collagen cross-linking and maturation, and thus affected the biogenesis of the extracellular matrix of cancer-associated fibroblasts and stellate cells in the tumor microenvironment." (PMID 35127477, 2021). "Based on these findings, we next wanted to determine whether PLOD2 deficiency regulates tumor cell metastatic capacity in vivo." (PMID 30563531, 2018). "Moreover, immunohistochemistry studies demonstrated increased PLOD2 expression associated with increasing tumor grade." (PMID 29165393, 2017).
tumor (continued). "Notably, high PLOD2 expression indicates tumor progression yet paradoxically associates with enhanced immunotherapy response through activation of immune escape pathways, thereby offering a potential therapeutic target for converting "cold tumors" into “hot tumors”." (PMID 41584042, 2026). "Besides, in a tumor microenvironment, PLOD2 could modulate the collagen–cross-linking activity of cancer-associated fibroblasts and promote tumor cell migration and invasion." (PMID 35141213, 2021). "However, PLOD2-deficient tumors had less stiffness which suggested that PLOD2 is an essential factor for collagen cross-links and associated with the biomechanical property of tumor." (PMID 29644003, 2018). "Across different cohorts, PLOD2 expression showed a positive correlation with tumor stage and Fuhrman grade in ccRCC." (PMID 41584042, 2026). "In cancer disease, increased PLOD2 expression indicates enhanced collagen deposition, fostering a desmoplastic reaction that promotes tumor progression by creating a supportive microenvironment for cancer cell proliferation and invasion." (PMID 40034261, 2025). "Mechanistically, this was linked to impaired expression of PLOD2 which is regulated by HIF-1α and critical for structuring the extracellular matrix in a way that facilitates tumor invasion." (PMID 41174561, 2025). "An in vivo study demonstrated that inhibition of PLOD2 reduced tumor growth and enhanced the efficacy of anti-PD-1 therapy, highlighting PLOD2 as a potential novel therapeutic target in UPS immunotherapy." (PMID 41300979, 2025). "PLOD2, as a key enzyme promoting stable collagen cross-linking, plays a crucial role in facilitating tumour cell motility, invasion, and proliferation." (PMID 40673276, 2025). "Recent advances have highlighted the pivotal role of PLOD2 in mediating hypoxia-driven tumor metastasis." (PMID 40775208, 2025). "IHC results elucidated the expression patterns of CKAP4 and PLOD2 in HCC tumour tissues and surrounding areas, providing visual evidence of their upregulation." (PMID 40673276, 2025). "Procollagen lysine 2-oxoglutarate 5-dioxygenase 2 (PLOD2) encodes LH2 and is a hypoxia-inducible gene that promotes metastasis in multiple tumor types." (PMID 40166934, 2025). "HIF-1α was shown to also enhance expression of collagen-modifying enzyme Procollagen-Lysine,2-Oxoglutarate 5-Dioxygenase 2 (PLOD2), facilitating a collagen structure conducive to tumor cell migration and lung colonization." (PMID 41174561, 2025). "Meanwhile, procollagen-lysine,2-oxoglutarate 5-dioxygenase 2 (PLOD2) gene has tumor-promoter effects in many types of cancers, including RCC." (PMID 38233403, 2024). "Based on our findings, we observed that PLOD2 + SAA1 + tumor cells were able to communicate with TME cells and act as strong senders and influencers in signaling pathways such as SPP1, MIF, PTN, and MK." (PMID 38951896, 2024). "We observed that the percentage of PLOD2 + SAA1 + tumor cells with high MECRGS scores, as well as the expression of immune checkpoints such as NECTIN2 and CD47, increased in patients who exhibited a partial response (PR) to immunotherapy." (PMID 38951896, 2024). "Previous studies have shown that PLOD2 expression can be induced by hypoxia thus affecting cell morphology, adherent ability, tumor migration and invasion ability." (PMID 38233403, 2024). "Mechanistically, METTL3 induces expression of tumor-promoting gene PLOD2 dependent on its methylase activity." (PMID 38233403, 2024). "Further analysis of a large RCC cohort from the TCGA dataset revealed a significant elevation in PLOD2 expression with increasing tumor grade." (PMID 38233403, 2024). "Subsequent investigation of the hub genes of the MECRGS model at the single-cell RNA level revealed that PLOD2, C1S, and C1R were primarily expressed in tumor cells." (PMID 38951896, 2024). "Next, we investigated PLOD2 + SAA1 + tumor cells’ interactions with other types of cells in the TME." (PMID 38951896, 2024).
tumor (continued). "The PLOD2 + SAA1 + tumor subtype displays intricate intercellular crosstalk and provides insights into the underlying molecular pathogenesis for ccRCC." (PMID 38951896, 2024). "Our study demonstrated that PLOD2 is identified as a novel marker for ccRCC progression through, and high PLOD2 expression indicates advanced tumor stage, lymph node metastasis, and poor overall survival." (PMID 38008826, 2023). "P4H2A and PLOD2 are vital for collagen posttranslational modification and remodeling of the tumor microenvironment and ECM leading to the formation of a stiff ECM and induction of cancer cell stemness and metastatic dissemination." (PMID 36826019, 2023). "Functional experiments revealed that knockdown of PLOD2 inhibited ccRCC cell proliferation, migration, invasion, and tumor growth in vivo." (PMID 38008826, 2023). "PLOD2 can participate in extracellular matrix remodeling by promoting the deposition of collagen fibers, thereby improving the invasiveness of tumor cells." (PMID 36936929, 2023). "A higher level of PLOD2 protein expression was also observed in the tumor tissues of patients with ccRCC compared to normal kidney tissues." (PMID 38008826, 2023). "In the Hannover cohort, GBM patients with high tumor levels of PLOD2 (PLOD2high) had a significantly shorter OS compared to patients with low levels of PLOD2 (PLOD2low) (p = 0.020; log-rank)." (PMID 35682709, 2022). "To determine the role of PLOD2 in tumor angiogenesis, we performed the tube formation assay, and the results showed that more capillary tubule formation was observed in si-NC group than si-PLOD2 group." (PMID 36276118, 2022). "Considering the role of PLOD2 in tumor angiogenesis in vitro, we performed IHC of angiogenesis related protein which including VEGF and CD31." (PMID 36276118, 2022). "PLOD2 was found as a key gene in mediating the formation of type I collagen, a major component of the tumor stroma in solid cancers." (PMID 36276118, 2022). "For instance, the expression of PLOD2 was found to be positively corelated with the activities of tumor-infiltrating immune cells(TIIC), including macrophages, neutrophils, CD4+T cells and B cells in HCC(B. 10)." (PMID 36276118, 2022). "To assess the levels of gene expression for all tumor stages, we compared PLOD2 expression in patients with different stages." (PMID 35586565, 2022). "The effect of PLOD2 on the anchorage-independent tumor growth was especially striking since PLOD2 knock-down led to almost a complete inhibition of colony formation in GBM cells." (PMID 35682709, 2022). "Although the tumor types differed, the relationship between PLOD2 expression and immune cells was similar." (PMID 35586565, 2022). "GBM cells produced soluble factors via PLOD2, which subsequently induced neutrophils to acquire a pro-tumor phenotype characterized by prolonged survival and the release of MMP9." (PMID 35682709, 2022). "Taken together these findings indicate that GBM cells release soluble factors via PLOD2, which stimulate neutrophils to acquire a tumor-promoting phenotype." (PMID 35682709, 2022). "Using U87 and U251 GBM cells, recent studies showed that PLOD2 enhanced the aggressiveness of GBM cells by promoting tumor invasion." (PMID 35682709, 2022). "Generally, PLOD2 plays an important role in both tumor growth and closely related to the prognosis of patients." (PMID 35586565, 2022). "Although the exact mechanisms are still largely unclear, PLOD2 can be expected to affect key signaling pathways in tumor cells, thereby modulating tumor progression." (PMID 35682709, 2022). "In previous studies, PLOD2 was reported to promote tumor metastasis by inducing collagen cross-linking." (PMID 36186418, 2022). "Fifty percent (19/38) of tumor tissue samples showed positive staining for PLOD2, with 74% of the samples displaying preferential staining of cells at the invasive front of the tumor tissue (blue arrow) and 26% stained throughout the tumor tissue." (PMID 33805564, 2021).
tumor (continued). "We found that PLOD2 is localized in the colonic crypts in the stem cell compartment of the normal mucosa and is found at increased levels in invasive areas of the tumor and, in some cases, throughout the tumor tissue." (PMID 33805564, 2021). "Then we checked the expression levels of PLOD2 in RCC tumor and adjacent tissues by RT-qPCR and IHC." (PMID 34179084, 2021). "Many lines of evidence suggested that PLOD2 is a tumor metastasis-promoting gene; it promotes tumor aggressive metastasis and invasion through mediating cross-links of collagen." (PMID 35141213, 2021). "In a few cases, weak staining for PLOD2 was also observed in the stroma around the tumor tissue (black arrows)." (PMID 33805564, 2021). "As an important modulator of fibrotic collagen, PLOD2 has been shown to promote tumor metastasis directly, by enhancing tumor cell migration, and indirectly, by inducing collagen reorganization." (PMID 33495412, 2021). "Accumulating evidence has suggested that PLOD2 has the effect of promoting tumor progression in various solid tumors." (PMID 34944486, 2021). "Histopathologically, PLOD2 was ubiquitously expressed in tumor cells (TCs) and fibroblast-like cells (FLCs) of OSCC patients but absent in tumor-infiltrating lymphocytes (TILs)." (PMID 34944486, 2021). "It has been reported that in sarcoma, pancreatic cancer and breast cancer, HIF-1α can regulate the expression of PLOD2 and thus affect tumor migration and invasion ability." (PMID 34179084, 2021). "Six have been indirectly linked to tumour malignancy and are thus new splicing targets to study (CAST, CSF1, PLOD2, SLK, SPAG9, TSC2)." (PMID 33845831, 2021). "In the CRC tissue, PLOD2 is expressed at increased levels, with a preference for the invasive edge of the tumor, suggesting that PLOD2 is involved in promoting human CRC cell invasion." (PMID 33805564, 2021). "Our preliminary experimental results showed that the incidence of tumor metastasis was significantly increased in RCC patients with elevated PLOD2 expression in cancer tissues, and overall survival rate was significantly reduced." (PMID 34179084, 2021). "Nevertheless, little is known about the specific spatial distribution of PLOD2 in different cell types in tumor microenvironment (TME)." (PMID 34944486, 2021). "The overexpression of PLOD2 can promote the crosslinking of collagen, increase the hardness of the extracellular matrix, and promote the proliferation and metastasis of tumor cells." (PMID 34258263, 2021). "Cells in the microenvironment, such as adipocytes and fibroblasts, play an important role in tumor progression; thus, we performed correlation analysis between PLOD2 and immune infiltration level in CESC." (PMID 34258263, 2021). "Western blot analysis proved that PLOD2 protein level was indeed elevated in OSCC tumor tissues (p < 0.001)." (PMID 34944486, 2021). "We found the mRNA and protein levels of PLOD2 were significantly increased in RCC tumor tissues compared to adjacent tissues." (PMID 34179084, 2021). "Data from Oncomine and TIMER2 both demonstrated that compared with normal tissues, PLOD2 mRNA level was significantly upregulated in tumor tissues in HNSCC patients." (PMID 34944486, 2021). "In this study, by using the HNSCC cases in TCGA database, we found significant increases of PLOD2 mRNA levels in tumor tissues compared with normal tissues, and highly expressed PLOD2 was associated with poor OS and DFS." (PMID 34944486, 2021). "CAF-derived ANGPTL2, WWTR1, and PLOD2 promote tumor progression and cell invasion, and MYO10 regulates CAF rigidity." (PMID 33917869, 2021). "Evidence has emerged that PLOD2 is involved in the regulation of extra matrix collagen and tumor metastasis through EMT, TGF-β, and hypoxia signals." (PMID 34944486, 2021). "In PDAC, increased expression of PLOD2 under hypoxic conditions promotes cell motility and thus facilitates tumour progression." (PMID 32958051, 2020).